NEFH (neurofilament heavy chain)
Description:
Neurofilaments usually contain three intermediate filament proteins: NEFL, NEFM, and NEFH which are involved in the maintenance of neuronal caliber. NEFH has an important function in mature axons that is not subserved by the two smaller NF proteins. May additionally cooperate with the neuronal intermediate filament proteins PRPH and INA to form neuronal filamentous networks (By similarity).
Synonyms: NF-H; NFH; CMT2CC
Tractability: PROTAC: ubiquitination databases record sites on it.
Gene: Protein-coding gene on chromosome 22 (29,480,218 to 29,491,390, forward strand). Ensembl gene ENSG00000100285.
Subcellular location: Cytoplasm, cytoskeleton; Cell projection, axon
Subcellular location (Human Protein Atlas): Basal body; Centrosome; Nuclear bodies; Cytosol; Nucleoplasm; Primary cilium; Primary cilium transition zone
Gene Ontology:
Molecular function: protein binding; protein kinase binding; structural constituent of cytoskeleton; dynein complex binding; kinesin binding; microtubule binding; protein-macromolecule adaptor activity; structural constituent of postsynaptic intermediate filament cytoskeleton
Biological process: axon development; axonal transport of mitochondrion; neurofilament bundle assembly; neuron projection organization; axonogenesis; intermediate filament bundle assembly; postsynaptic intermediate filament cytoskeleton organization; postsynaptic modulation of chemical synaptic transmission
Cellular component: cytoplasm; cytoskeleton; neurofibrillary tangle; axon; neurofilament; axon cytoplasm; postsynaptic density; postsynaptic intermediate filament cytoskeleton; Schaffer collateral - CA1 synapse
Genetic constraint (gnomAD): Loss-of-function variants: 58 observed, 50.94 expected, observed/expected ratio (o/e) 1.14, 90% interval 0.92 to 1.42. The upper end of that interval is the gene's LOEUF score, 1.42, which puts it in group 5 of 6, group 1 being the genes least tolerant of losing a copy. Missense variants: 1,221 observed, 1,213.6 expected, observed/expected ratio (o/e) 1.01, 90% interval 0.96 to 1.05. Synonymous variants: 542 observed, 501.4 expected, observed/expected ratio (o/e) 1.08, 90% interval 1.01 to 1.16.
Gene-disease validity (ClinGen):
ClinGen rates the evidence that NEFH causes each of these diseases.
Charcot-Marie-Tooth disease axonal type 2CC (autosomal dominant): Definitive. Any Charcot-Marie-Tooth disease in which the cause of the disease is a mutation in the NEFH gene.
amyotrophic lateral sclerosis (autosomal dominant): Limited. Amyotrophic lateral sclerosis (ALS) is a neurodegenerative disease characterized by progressive muscular paralysis reflecting degeneration of motor neurons in the primary motor cortex, corticospinal tracts, brainstem and spinal cord.
Homologues: Orthologues: chimpanzee NEFH (99% identical), macaque NEFH (95% identical), rabbit NEFH (83% identical), rat Nefh (81% identical), mouse Nefh (80% identical), Caenorhabditis elegans F35A5.1 (30% identical).
Diseases named in the same sentence as NEFH in open-access papers:
NEFH is named in the same sentence as 124 diseases in open-access papers, as found by Europe PMC text mining. Sharing a sentence is not in itself a finding about the gene and the disease. The quoted sentences say what the papers report.
amyotrophic lateral sclerosis (27 papers, 2009 to 2026). "Variant filtering identified potentially deleterious mutations in three known disease genes: DCTN1, KIF5A and NEFH, which have been all associated with similar clinical presentations of amyotrophic lateral sclerosis, Parkinsonism and/or hereditary spastic paraplegia." (PMID 25957632, 2015). "The NEFH gene has been implicated in amyotrophic lateral sclerosis (ALS), a progressive motor neuron degeneration that leads to paralysis and death." (PMID 35982790, 2022). "As delineated in preceding sections, both NEFH and TUBA4A demonstrate robust associations with amyotrophic lateral sclerosis (ALS)." (PMID 41394403, 2025). "The phosphorylated neurofilament heavy chain (pNfH) is a promising biomarker in amyotrophic lateral sclerosis (ALS)." (PMID 35715961, 2022). "Circulating protein aggregates are enriched with neurofilament heavy chain—axonal proteins involved in brain aggregate formation and recently identified as biomarkers of the fatal neuromuscular disorder amyotrophic lateral sclerosis." (PMID 34396108, 2021). "The alterations in NEFH expression or function may disrupt brainstem homeostasis and neural circuitry integrity, potentially contributing to the pathogenesis of amyotrophic lateral sclerosis (ALS) and related neurological disorders." (PMID 41394403, 2025). "The Amyotrophic Lateral Sclerosis rating scale revised (ALSFRS-R) was used in two studies, showing disease progression in one but not the other, and was shown to correlate with serum and CSF neurofilament heavy chain, though one paper included patients with ALS in their analysis." (PMID 37761896, 2023). "These include genes in the pathways for amyotrophic lateral sclerosis (NEF3, NEFL, NEFH), Huntington's disease (CALM3, CLTC, CLTB), neurodegenerative disorders (APLP1, NEFH, FBXW7), Parkinson's disease (GPR37) and prion disease (APLP1, NFE2L2)." (PMID 19948073, 2009).
Alzheimer disease (10 papers, 2008 to 2025). A progressive, neurodegenerative disease characterized by loss of function and death of nerve cells in several areas of the brain leading to loss of cognitive function such as memory and language. "A recent study reported on a statistically significant inverse relationship between avidity and levels of antibodies against neurofilament heavy chain in healthy blood donors, as well as patients with Alzheimer's disease." (PMID 29617422, 2018). "The possibility of increased protein synthesis has been ruled out in degenerating neurons of ALS and Alzheimer disease patients in which NEFL mRNA levels are downregulated, whereas the transcript levels for NEFM or NEFH usually remain unchanged." (PMID 27021905, 2016).
prostate carcinoma (6 papers, 2020 to 2025). A carcinoma that arises from epithelial cells of the prostate gland. "NEFH functions as a tumor suppressor, while MSMB encodes a prostate-secreted protein and biomarker for prostate cancer." (PMID 41468516, 2025). "Our study reveals that SLC14A1, ARHGEF38, NEFH, MSMB, KRT23, and KRT15 are potential diagnostic biomarkers for prostate cancer, among which MSMB may play a protective role in prostate cancer." (PMID 40260298, 2025). "Neurofilament heavy chain (NEFH) is a protein that is, in addition to the central nervous system and in peripheral nerves, also expressed by normal prostate epithelial cells but downregulated in prostatic carcinomas." (PMID 33114768, 2020).
Cognitive impairment (4 papers, 2019 to 2025). Abnormal cognition is characterized by deficits in thinking, reasoning, or remembering. "The proteins associated with these neuroprotective effects (HTT, NEFH and NEFL) are potential drug targets for the treatment of obesity-induced cognitive impairment with semaglutide." (PMID 36998046, 2023).
motor neuron disease (4 papers, 2017 to 2024). "Our results thus provide a physiological basis to the pathogenicity of NEFH mutations that interfere with neurofilament assembly via protein sequestration and cause neurotoxicity, which explains the overlapping clinical features of NEFH mutations with those of motor neuron disease." (PMID 28709447, 2017).
spinal muscular atrophy (4 papers, 2019 to 2024). A motor neuron disease that affect the muscles, and characterized by muscle weakness and atrophy resulting from progressive degeneration and irreversible loss of the anterior horn cells in the spinal cord (i.e., lower motor neurons) and the brain stem nuclei. "Recently, the Paris model was adapted to analyze the dynamics of neurofilament heavy chain (NfH) in pediatric patients with spinal muscular atrophy (SMA) and the effects of treatment." (PMID 39022122, 2024). "Biomarkers capable of reflecting disease onset and short- and long-term therapeutic effects in individuals with spinal muscular atrophy (SMA) are still an unmet need and phosphorylated neurofilament heavy chain (pNF-H) holds significant promise." (PMID 38756215, 2024).
Charcot-Marie-Tooth disease (3 papers, 2018 to 2023). An inherited degenerative disorder involving the peripheral nerves. "In particular, the NEFL and NEFH genes are mutated in Charcot-Marie-Tooth (CMT) disease, the most common inherited neurological disorder of the peripheral nervous system." (PMID 38164457, 2023). "In this review, we will focus on Charcot-Marie-Tooth (CMT) disease, for which NEFL and NEFH are causal genes." (PMID 38164457, 2023).
Charcot-Marie-Tooth disease type 2 (3 papers, 2017 to 2022). A Charcot-Marie-Tooth disease characterized by abnormalities in the axon of the peripheral nerve cell. "Whole-exome sequencing also detected a suspected pathogenic mutation in the axonal NEFH genes related to Charcot-Marie-Tooth disease type 2." (PMID 35299674, 2022). "Neurofilament heavy chain (NEFH) gene was recently identified to cause autosomal dominant axonal Charcot-Marie-Tooth disease (CMT2cc)." (PMID 28709447, 2017). "Mutations in the NEFL gene cause Charcot-Marie-Tooth disease type 2 (CMT2) and mutations of NEFH and neurofilament hyperphosphorylations are associated with ALS, AD, and PD." (PMID 31252669, 2019).
epilepsy (3 papers, 2018 to 2024). A brain disorder characterized by episodes of abnormally increased neuronal discharge resulting in transient episodes of sensory or motor neurological dysfunction, or psychic dysfunction. "Notably, NEFH protein was described 1.5-fold up-regulated in children with cortical dysplasia with epilepsy." (PMID 30567555, 2018).
multiple sclerosis (3 papers, 2008 to 2025). A progressive autoimmune disorder affecting the central nervous system resulting in demyelination. "Background/Objective: Neurofilament light chain (Nf-L), neurofilament heavy chain (Nf-H), and chitinase 3-like 1 (CHI3L1) are cerebrospinal fluid (CSF) biomarkers of neuroaxonal damage and inflammation in multiple sclerosis (MS)." (PMID 40564113, 2025).
breast carcinoma (2 papers, 2020 to 2024). "Reintroducing NEFH expression in breast cancer cells reduced invasiveness, suggesting that expression of neuronal filaments in cancer induced a rearrangement of the cytoskeleton that reduced motility and migration." (PMID 33315971, 2020).
cardiac arrest (2 papers, 2012 to 2020). Cessation of breathing and/or cardiac function. "Here we tested whether a biomarker for neurodegeneration, the neurofilament heavy chain (NfH), may improve diagnostic accuracy in the first days after cardiac arrest." (PMID 22410303, 2012).
esophageal cancer (2 papers, 2010 to 2024). A primary or metastatic malignant neoplasm involving the esophagus. "Immunohistochemical analysis of NEFH in esophageal cancer tissue microarray with normal tissue controls (ES804)." (PMID 20140245, 2010). "Since the NEFH promoter was specifically methylated in tumor tissues and its expression was down-regulated in ESCC, NEFH might function as a tumor suppressor in esophageal cancer." (PMID 20140245, 2010).
glaucoma (2 papers, 2008 to 2023). Increased pressure in the eyeball due to obstruction of the outflow of aqueous humor. "Two NEFH antibodies were used to examine the localization of upregulated NEFH in the axons of optic nerves of healthy and experimental glaucoma monkeys." (PMID 18822132, 2008). "Staining with an antibody that recognizes predominantly phosphorylated NEFH revealed presumptive growth cone-like structures in the post laminar optic nerves of monkeys with experimental glaucoma, which also were positive for GAP43, whereas these structures were absent in control monkeys." (PMID 18822132, 2008). "Two genes, NEFH and GPNMB, exhibited higher fold increases in samples with moderate to advanced glaucoma." (PMID 18822132, 2008). "The appearance of GAP43+ and phospho-NEFH+ growth cone-like structures in the optic nerve has not been previously reported in the nonhuman primate model or in human glaucoma." (PMID 18822132, 2008).
Huntington disease (2 papers, 2009 to 2013). Huntington disease (HD) is a rare neurodegenerative disorder of the central nervous system characterized by unwanted choreatic movements, behavioral and psychiatric disturbances and dementia. "The BAD, NEFH, NEFL and DERL1 genes are also involved in Huntington’s disease pathways." (PMID 23782433, 2013).
renal cell carcinoma (2 papers, 2014 to 2017). "For instance, the variants of NEFH gene, a tumor suppressor, were suggested as prognostic markers for renal cell carcinoma (RCC) and contributed to susceptibility of esophageal squamous cell and hepatocellular carcinomas." (PMID 28249600, 2017).
secondary progressive MS (2 papers, 2025). "Neurofilament heavy chain (NfH) levels have been less investigated compared to the NfLs and even though the studies outlined a significant difference between relapsing–remitting MS and secondary progressive MS, this difference does not seem to have any clinical significance." (PMID 40362691, 2025).
tauopathies (2 papers, 2022 to 2023). "The neurofilament light chain (NfL), phosphorylated neurofilament heavy chain (pNfH) and chitinase-3-like protein 1 (YLK-40) were described as statistically significant CSF differentiating biomarkers to discriminate tauopathies and synucleinopathies." (PMID 36553028, 2022).
bacterial meningitis (1 paper, 2024). Inflammation of the membranes surrounding the brain and spinal cord due to a bacterial infection. "In children, the CSF concentrations of the neurofilament heavy chain (NfH) were increased in bacterial meningitis compared with controls, with higher NfH long-term levels in children with neurological sequelae." (PMID 38539395, 2024).
benign prostatic hyperplasia (1 paper, 2021). A non-cancerous nodular enlargement of the prostate gland. "Furthermore, differential quantitative proteomic analysis of patients with PCa and benign prostatic hyperplasia (BPH) showed a significant decrease in FKBP5, FAM129A, RAB27A, FASN, NEFH proteins after local PCa treatment." (PMID 33810357, 2021).
breast tumors (1 paper, 2021). "It was reported that methylation-mediated inactivation of NEFH, NEFL or NEFM was common in primary breast tumors compared to normal breast tissues and correlated with clinical features of disease progression." (PMID 34001208, 2021).
cardiomyopathy (1 paper, 2020). A disease of the heart muscle or myocardium proper. "Data analysis also indicated that there are many genes related to cardiomyopathy, such as TTN, NEFH, PLEC, CASQ2, and SYNE1." (PMID 33200202, 2020).
cervical cancer (1 paper, 2021). A primary or metastatic malignant neoplasm involving the cervix. "During the progression of cervical cancer, from normal cervical tissues to CIN 1, 2 and 3, the up‐regulated genes we confirmed were SYCP2, NEFH, CDKN2A and KRT17." (PMID 33624385, 2021).
deafness (1 paper, 2018). An inherited or acquired condition characterized by the complete loss of the ability to hear from one or both ears. "We have identified putative causal variants in known deafness genes and several novel candidate genes, including NEDD4 and NEFH that were mutated in multiple individuals." (PMID 30180840, 2018).
Encephalopathy (1 paper, 2021). Encephalopathy is a term that means brain disease, damage, or malfunction. "However, the molecular contributors to PGC-1α knockout-related encephalopathy likely also involve the deficiency of a number of other PGC-1α putative targets, such as the neurofilament heavy chain (NEFH)." (PMID 35052512, 2021).
esophageal squamous cell carcinoma (1 paper, 2010). Esophageal squamous cell carcinoma (ESCC) is a type of esophageal carcinoma (EC) that can affect any part of the esophagus, but is usually located in the upper or middle third. "We observed promoter methylation and loss of expression in neurofilament heavy polypeptide (NEFH) in a significant proportion of primary esophageal squamous cell carcinoma (ESCC) samples that were of a high tumor grade and advanced stage." (PMID 20140245, 2010).
focal segmental glomerulosclerosis (1 paper, 2018). A renal disorder characterized by sclerotic lesions in the glomeruli. "In addition, NEFH expression was significantly increased in renal biopsy specimens from patients with focal segmental glomerulosclerosis and membranous nephropathy, but in those with minimal change disease." (PMID 30464326, 2018).
glioma (1 paper, 2008). A benign or malignant brain and spinal cord tumor that arises from glial cells (astrocytes, oligodendrocytes, ependymal cells). "For example, among the neurofilament genes (INA, NEFH, NEFM, NEFL) present in cluster C, alphainternexin (INA) was the only one overexpressed in both gliomas with 1p19q codeletion and cortex samples in comparison to gliomas with EGFR amplification." (PMID 18492260, 2008).
glomerular diseases (1 paper, 2018). "In this study, we identified NEFH as a new IF that was upregulated in ADR-injured podocytes and in human glomerular diseases (FSGS and MN)." (PMID 30464326, 2018). "The present study provided evidence of NEFH upregulation in human FSGS and MN and showed that NEFH is a novel IF that helps protect podocytes in glomerular diseases." (PMID 30464326, 2018).
head and neck cancer (1 paper, 2024). A primary or metastatic malignant neoplasm affecting the head and neck. "There has been previous evidence of differential expression of e.g. NEFH, ZRF2,TAF7L, ZNF541 and TYMS in head and neck cancer, related to HPV status." (PMID 38643268, 2024).
hemorrhagic stroke (1 paper, 2025). A stroke caused by a bleed on the brain. "Although the neurofilaments were often assessed in the cerebrospinal fluid (CSF) and just a few days after the hemorrhagic stroke, the majority of these studies discovered a correlation between the levels of neurofilament heavy chain (NfH) and the clinical illness." (PMID 40304765, 2025).
Intellectual disability (1 paper, 2018). "This gene has previously been implicated in intellectual disability and is apparently linked to FMR1 and NEFH overexpression associated with neurological disorders." (PMID 30567555, 2018).
liposarcoma (1 paper, 2018). A usually painless malignant tumor that arises from adipose tissue. "In addition, fused in sarcoma/translocated in liposarcoma (FUS/TLS), another ALS-associated protein, has been shown to bind to murine NEFL, NEFM and NEFH transcripts." (PMID 30029677, 2018).
lymphoma (1 paper, 2020). A malignant (clonal) proliferation of B- lymphocytes or T- lymphocytes which involves the lymph nodes, bone marrow and/or extranodal sites. "These mutations, which impact the edge of an exon, have potential to affect NEFH splicing, but since they are the same length and occur in the same region, these mutations are probably not relevant to the pathogenesis of lymphoma." (PMID 32857815, 2020).
neurofibromatosis type 2 (1 paper, 2010). "The neurofilament heavy polypeptide (NEFH, 200 kD) gene resides at chromosomal band 22q12.2 and was proposed as a DNA marker for presymptomatic diagnosis in neurofibromatosis type 2 (NF2) families." (PMID 20140245, 2010).
oligodendroglioma (1 paper, 2020). A well-differentiated (WHO grade II), diffusely infiltrating neuroglial tumor, typically located in the cerebral hemispheres. "In our cohort, tumors expressing canonical neuronal markers like neurofilament (NEFL, NEFM, and NEFH) and synaptophysin (SYP) were significantly localized within the expression space of oligodendrogliomas (q-value < 0.015)." (PMID 32732999, 2020).
pharyngeal squamous cell carcinoma (1 paper, 2024). A squamous cell carcinoma that arises from the pharynx. "Notably, some authors have already found hypermethylation of NEFH (protein kinase binding and microtubule binding), in pharyngeal squamous cell carcinoma, which significantly correlated with HPV positivity." (PMID 38643268, 2024).